CKAP4 (cytoskeleton associated protein 4)
Description:
Mediates the anchoring of the endoplasmic reticulum to microtubules. High-affinity epithelial cell surface receptor for the FZD8-related low molecular weight sialoglycopeptide APF/antiproliferative factor. Mediates the APF antiproliferative signaling within cells.
Synonyms: Climp-63; p63; CLIMP63; ERGIC-63
Tractability: Antibody: UniProt places it where antibodies can reach, with high confidence; its Gene Ontology location is reachable by antibodies, with high confidence; UniProt predicts a signal peptide or a membrane-spanning region. PROTAC: ubiquitination databases record sites on it; its protein half-life has been measured.
Gene: Protein-coding gene on chromosome 12 (106,237,880 to 106,304,279, reverse strand). Ensembl gene ENSG00000136026.
Subcellular location: Endoplasmic reticulum membrane; Cell membrane; Cytoplasm, cytoskeleton; Cytoplasm, perinuclear region
Subcellular location (Human Protein Atlas): Endoplasmic reticulum; Mitochondria; Nuclear speckles
Pathways (Reactome):
Metabolism of proteins: Post-translational protein phosphorylation; Regulation of Insulin-like Growth Factor (IGF) transport and uptake by Insulin-like Growth Factor Binding Proteins (IGFBPs); Surfactant metabolism
Signal Transduction: RND2 GTPase cycle; RND3 GTPase cycle
Immune System: Neutrophil degranulation
Gene Ontology:
Molecular function: protein binding; RNA binding
Cellular component: endoplasmic reticulum; endoplasmic reticulum membrane; extracellular exosome; lipid droplet; plasma membrane; rough endoplasmic reticulum; azurophil granule membrane; endoplasmic reticulum lumen; lamellar body; membrane; specific granule membrane; cytoskeleton; perinuclear region of cytoplasm
Genetic constraint (gnomAD): Loss-of-function variants: 21 observed, 21.95 expected, observed/expected ratio (o/e) 0.96, 90% interval 0.68 to 1.38. The upper end of that interval is the gene's LOEUF score, 1.38, which puts it in group 5 of 6, group 1 being the genes least tolerant of losing a copy. Missense variants: 666 observed, 659.4 expected, observed/expected ratio (o/e) 1.01, 90% interval 0.95 to 1.08. Synonymous variants: 338 observed, 301.83 expected, observed/expected ratio (o/e) 1.12, 90% interval 1.02 to 1.23.
Homologues: Orthologues: chimpanzee CKAP4 (98% identical), macaque CKAP4 (97% identical), dog CKAP4 (83% identical), pig CKAP4 (82% identical), rat Ckap4 (80% identical), mouse Ckap4 (80% identical), rabbit CKAP4 (68% identical), guinea pig CKAP4 (59% identical), Caenorhabditis elegans citk-2 (14% identical), Caenorhabditis elegans citk-1 (13% identical), Drosophila melanogaster SMC3 (13% identical), Caenorhabditis elegans smc-3 (11% identical). Paralogues in human: SMC1B (18% identical), SMC1A (16% identical), SMC2 (15% identical), SMC3 (14% identical), SMC4 (14% identical), CCDC157 (11% identical), CCDC122 (7% identical).
Diseases named in the same sentence as CKAP4 in open-access papers:
CKAP4 is named in the same sentence as 77 diseases in open-access papers, as found by Europe PMC text mining. Sharing a sentence is not in itself a finding about the gene and the disease. The quoted sentences say what the papers report.
pancreatic cancer (17 papers, 2020 to 2025). "Hirokazu Kimura’s research has found that cytoskeleton-associated protein 4 (CKAP4) is significantly detectable in the blood serum of pancreatic tumor xenograft mice as well as patients diagnosed with PC." (PMID 41024179, 2025). "Research indicates that the overexpression of cytoskeleton-associated protein 4 (CKAP4) or LDL receptor-related protein 6 (LRP6) facilitates the development of pancreatic cancer." (PMID 40066091, 2025). "Published studies suggested that overexpression of cytoskeleton associated protein 4 (CKAP4) or LDL receptor‐related protein 6 (LRP6) promotes pancreatic cancer progression." (PMID 36018061, 2023). "Recently, scholars have successively discovered MEK1/2 inhibition (MEKi), DNA methyltransferase 1 (DNMT1), and cytoskeleton-associated protein 4 (CKAP4) and other therapeutic targets for pancreatic cancer, but it still needs further clinical verification." (PMID 36505775, 2022). "A Dickkopf 1 (DKK1) receptor cytoskeleton-associated protein 4 (CKAP4) has been proposed as a biomarker, which is secreted with exsosomes from pancreatic cancer cells." (PMID 35159011, 2022). "In murine models, the anti-CKAP4 antibodies repressed lymph node metastasis of pancreatic cancer and increased survival." (PMID 41149482, 2025). "A humanized anti-CKAP4 antibody showed efficacy against pancreatic cancer in murine cancer models by inhibiting the DKK1-CKAP4 axis." (PMID 39795613, 2025). "Recent studies have demonstrated a novel pathway where DKK1 binds to its novel receptor CKAP4 and activates the Akt-signaling pathway for cancer progression in lung cancer, pancreatic cancer, and esophageal cancer." (PMID 39858622, 2025). "Blockade of the DKK1-CKAP4 binding by anti-CKAP4 monoclonal antibody inhibits xenograft tumor formation and metastasis of pancreatic cancer cells and extends survival of mice." (PMID 35159011, 2022). "High expression of CKAP4 is detected in pancreatic cancer patient sera and in sera of pancreatic cancer cell-xenografted mice." (PMID 35159011, 2022). "Another study showed CKAP4 not only regulated the migration of pancreatic cancer cell by relying on DKK1, but also mediated integrin trafficking independently of DKK1." (PMID 33614703, 2020). "The formation of the xenograft tumors derived from CKAP4-depleted cells, including lung cancer cells, pancreatic cancer cell, and ESCC cells, was much less than that of control tumors." (PMID 33614703, 2020). "Taken together, CKAP4 regulated pancreatic cancer cell adhesion and migration through interaction with and recycling of α5β1 integrin." (PMID 33614703, 2020). "At present, there have been studies examining the serum levels of CKAP4 in various cancers, including hepatocellular carcinoma, lung cancer, pancreatic cancer, and ESCC." (PMID 33614703, 2020). "For instance, CKAP4 is detected in exosomes harvested from the serum of patients with pancreatic cancer and reflects its expression in tumor lesions, which may represent a biomarker for pancreatic cancer." (PMID 34434900, 2021). "The results showed that serological level of CKAP4 is directly related to the tumor lesions and CKAP4 secreted with exosomes into serum may represent a biomarker for pancreatic cancer." (PMID 33614703, 2020). "In S2-CP8 pancreatic cancer cells, endogenous CKAP4 formed a complex with p85α." (PMID 33614703, 2020). "Moreover, either DKK1 or CKAP4 knockdown suppressed cell growth in vitro and xenograft tumor formation via the Akt signaling pathway, and anti-CKAP4 antibody has also been demonstrated to show an antitumor effect in pancreatic cancer cells." (PMID 40282454, 2025). "Many studies have shown that CKAP4 has been related to various cancers including bladder cancer, cervical carcinoma, lung cancer, cholangiocarcinoma, hepatocellular carcinoma, esophageal squamous cell carcinoma, pancreatic cancer, glioma, clear cell renal cell carcinoma, and so on." (PMID 33614703, 2020).
pancreatic cancer (continued). "Therefore, CKAP4 mediated pancreatic cancer cell proliferation by PI3K/AKT signal pathway." (PMID 33614703, 2020). "S-palmitoylation promotes the location of CKAP4 and LRP6 within detergent-resistant membrane (DRM) fractions, activating the PI3K-AKT pathway and enhancing pancreatic cancer cell proliferation." (PMID 40066091, 2025). "In a study on lung and pancreatic cancer, co-expression of DKK1 and CKAP4 was found to be negatively correlated with the prognosis and recurrence-free survival of pancreatic and lung cancer." (PMID 39107271, 2024). "For instance, CKAP4 is a receptor for Dickkopf-1 (DKK1) proteins and is also a potential molecular marker of pancreatic cancer." (PMID 34671013, 2021). "On the other hand, CKAP4 mediated integrin trafficking independently of DKK1 and affected pancreatic cancer cell migration." (PMID 33614703, 2020). "Furthermore, CKAP4 has been detected in rat as well as human serum in various cancers like hepatocellular carcinoma (HCC), lung cancer, and pancreatic cancer." (PMID 41149482, 2025).
lung carcinoma (15 papers, 2018 to 2025). "Compared to healthy controls (HCs), serum exosomal CKAP4 positivity was greater in lung cancer patients and serves as a lung cancer diagnostic biomarker." (PMID 39757782, 2025). "Diagnostic serum markers are also in high demand for the early detection of lung cancer, and two strong biomarker candidates, cytoskeleton-associated protein 4 (CKAP4) and calnexin (CANX), have been identified using RPPAs." (PMID 39147028, 2024). "Serum CKAP4 levels can distinguish lung cancer patients from healthy controls, making it a potential serum diagnostic marker for lung cancer." (PMID 37508851, 2023). "Further, they analyzed CKAP4 diagnostic value in 271 lung cancer patients and 100 healthy controls." (PMID 33614703, 2020). "Kumar and co-workers developed a highly sensitive electrochemical immunosensor using a nanoengineered material of magnesium oxide (MgO) on functionalized MWCNTs (f-MWCNT), further modified with APTES, for the early diagnosis of lung cancer biomarker CKAP4." (PMID 40509251, 2025). "To explore the possibility of Si QD micelles-CKAP4 targeting lung cancer tissues, we designed an in vitro experiment to verify the targeting property of Si QD micelles-CKAP4 to A549 tissues." (PMID 34331597, 2021). "In this study, cytotoxicity tests showed that Si QD micelles-CKAP4 exhibited selective cytotoxicity to lung cancer cells at 9.5–19 μg/mL." (PMID 34331597, 2021). "Si QD micelles-CKAP4 is expected to be used as an optical contrast agent for navigation in lung cancer surgery in the future." (PMID 34331597, 2021). "This phenomenon contributed to the targeting ability of the Si QD micelles-CKAP4 to lung cancer tissues." (PMID 34331597, 2021). "Compared with the nanomaterials that passively target tumors via the EPR effect, Si QD micelles-CKAP4 showed stronger specificity to lung cancer tissue." (PMID 34331597, 2021). "Si QD micelles-CKAP4 is a specifically targeted imaging agent for lung cancer and is expected to be a fluorescent contrast agent for lung cancer surgical navigation in the future." (PMID 34331597, 2021). "A recent study identified that serum CKAP4 levels of lung cancer patients were significantly higher than those of healthy controls, suggesting CKAP4 as a potential early biomarker for lung cancer." (PMID 33737684, 2021). "In serum, lung cells, and tissues of the lung cancer patients, CKAP4 had been detected to be significantly higher than those of the healthy controls." (PMID 33078369, 2021). "Due to the conjugation of antibody, Si QD micelles-CKAP4 showed good targeting ability to lung cancer cells and tissues both in vitro and in vivo." (PMID 34331597, 2021). "CKAP4, which functions as a receptor of various ligands, is detected on the cell surface membrane of lung cancer cells." (PMID 34671013, 2021). "Laser confocal microscopy and fluorescence microscopy assay showed that the Si QD micelles-CKAP4 exhibited good targeting ability to lung cancer cells and lung cancer tissues in vitro." (PMID 34331597, 2021). "Si QD micelles-CKAP4 exhibited good targeting ability to lung cancer cells and lung cancer tissues both in vitro and in vivo." (PMID 34331597, 2021). "The results showed that the serum CKAP4 levels were obviously higher in lung cancer patients than in healthy persons." (PMID 33614703, 2020). "CKAP4 regulates its release from lung cancer cells to exosomes via palmitoylation." (PMID 40977744, 2025). "Therefore, as a result of CKAP4 antibody conjugation, the cytotoxicity of Si QD micelles-CKAP4 to normal cells was significantly less than that of lung cancer cells, which provides a powerful condition for the biological application of Si QD micelles-CKAP4." (PMID 34331597, 2021). "Therefore, only A549 cells cannot fully reflect the targeting ability of the Si QD micelles-CKAP4 to lung cancer." (PMID 34331597, 2021).
lung carcinoma (continued). "In this study, human lung cancer cell line A549 and human renal epithelial cell line 293 T were used as target cells to investigate the targeting ability of Si QD micelles and Si QD micelles-CKAP4." (PMID 34331597, 2021). "Owing to the conjugation of CKAP4 antibody, Si QD micelles-CKAP4 could actively target lung cancer tissue." (PMID 34331597, 2021). "This study successfully synthesized Si QD micelles-CKAP4, which could target the imaging of lung cancer tissues." (PMID 34331597, 2021). "In addition, these results also indicated that Si QD micelles-CKAP4 showed higher biological safety in normal cells than in lung cancer cells, which laid a foundation for its application in vivo." (PMID 34331597, 2021). "The human lung cancer cell line A549 and human renal epithelial cell line 293 T were used as target cells to investigate the biosafety of Si QD micelles and Si QD micelles-CKAP4." (PMID 34331597, 2021). "In addition, Si QD micelles-CKAP4 specifically targeted lung cancer tissue in vivo compared with healthy lung tissue." (PMID 34331597, 2021). "Nagashio and coworkers observed that CKAP4 was expressed in fibroblasts of the tumor stroma and the cytoplasm of tumor cells but not in normal lung specimens in tissue chips containing 70 consecutive pairs of lung cancers." (PMID 33614703, 2020). "Downregulation of CKAP4 or DKK1 in A549 lung cancer cells suppressed AKT activity through PI3K." (PMID 33614703, 2020). "CKAP4 could be a key target for developing novel lung cancer therapeutic strategies." (PMID 40977744, 2025). "Thus, CKAP4 stands as an early serodiagnostic marker for lung cancer and respiratory distress." (PMID 33078369, 2021). "Therefore, CKAP4 antibody-conjugated Si QD micelles might be a novel fluorescent contrast agent, which might be used as a fluorescent contrast agent for navigation in lung cancer surgery." (PMID 34331597, 2021). "Recent studies have found that CKAP4 can be detected in the serum of HCC, pancreatic ductal adenocarcinoma, esophageal squamous cell carcinoma, and lung cancer patients." (PMID 33614703, 2020). "Taken together, these studies have showed that CKAP4 is expected to be a serological marker for HCC, lung cancer, PDAC, and ESCC." (PMID 33614703, 2020). "Indeed, CKAP4 located in the plasma membrane has been found to be secreted via exosomes by pancreatic duct adenocarcinoma (PDAC) and lung cancer cells both in vitro and in vivo, resulting in detection of CKAP4 in mice and human serum." (PMID 41149482, 2025). "Moreover, CKAP4 is secreted into the serum with exosomes in tumors and is expected to be a novel serological marker for diagnosis of HCC, lung cancer, PDAC, and ESCC." (PMID 33614703, 2020).
hepatocellular carcinoma (8 papers, 2020 to 2025). A malignant tumor that arises from hepatocytes. "Moreover, the co-expression of DKK1 and CKAP4 is associated with hepatocellular carcinoma (HCC) invasion and poor prognosis." (PMID 37835450, 2023). "The reported substrates of ZDHHC2 also includes CD9 and CD151 in HEK293 cells, Lck in T cells, and CKAP4 in hepatocellular carcinoma and interstitial cystitis." (PMID 32587588, 2020). "Conversely, high expression of CKAP4 was found to be consistent with longer overall survival (OS) in patients with cholangiocarcinoma and hepatocellular carcinoma (HCC), indicating that the cellular context might influence the function of CKAP4." (PMID 35355709, 2022). "However, there are opposing reports about CKAP4 as an anticancer protein in various kinds of tumors, such as hepatocellular carcinoma (HCC), intrahepatic cholangiocellular carcinoma (ICC), and glioma." (PMID 33614703, 2020). "In hepatocellular carcinoma, DKK1′s interaction with CKAP4 increases PD-L1 expression as well." (PMID 41149482, 2025). "Our group investigated the relationship between CKAP4/DHHC2 expression and prognosis in 416 patients with hepatocellular carcinoma (HCC)." (PMID 33614703, 2020).
esophageal cancer (7 papers, 2019 to 2025). A primary or metastatic malignant neoplasm involving the esophagus. "DKK3 was previously shown to bind to Cytoskeleton-Associated Protein 4 (CKAP4) on esophageal cancer cells, and DKK3 and CKAP4 were found to be required for the phosphorylation of the Akt serine/threonine kinase in HNSCC cell lines." (PMID 38022675, 2023). "In pancreatic and esophageal cancers, DKK1 can bind to its receptor cytoskeleton‐associated protein 4 (CKAP4) and then activate the PI3K–AKT pathway to promote tumor growth." (PMID 38525111, 2024). "In esophageal cancer (ESCA), DKK1 promoted cell proliferation through the cytoskeleton-associated protein 4 (CKAP4)-related pathway." (PMID 34899842, 2021). "CKAP4 (cytoskeleton-associated protein 4) was identified as Dickkopf1 (DKK1) receptor, which is correlated with prognosis in pancreatic, lung, and esophageal cancers, and the DKK1 signaling pathway was always activated during cancer cell proliferation." (PMID 31360146, 2019). "In addition, CKAP4 is up-regulated in various tumors, including clear cell renal cell carcinoma and esophageal cancer, which intensifies tumor cell metastasis." (PMID 34596006, 2021).
esophageal squamous cell carcinoma (7 papers, 2020 to 2025). Esophageal squamous cell carcinoma (ESCC) is a type of esophageal carcinoma (EC) that can affect any part of the esophagus, but is usually located in the upper or middle third. "In surgically resected esophageal squamous cell carcinoma, patients with both CKAP4 and DKK1 positivity showed significantly worse overall survival and RFS than those negative for both biomarkers." (PMID 40282454, 2025). "Simultaneous expression of DKK1 and CKAP4 is associated with poor prognosis in pancreatic ductal adenocarcinoma (PDAC), lung adenocarcinoma and squamous cell carcinoma, and esophageal squamous cell carcinoma (ESCC) patients." (PMID 34117362, 2021). "It has been reported that the expression of CKAP4 is elevated in esophageal squamous cell carcinoma (ESCC) specimens and it is correlated to poorer prognosis." (PMID 41149482, 2025). "For instance, in esophageal squamous cell carcinoma (ESCC), the DKK1 and CKAP4 interaction is considered one of the key mechanisms driving ESCC cell proliferation and tumor formation." (PMID 37835450, 2023).